UPK3A (uroplakin 3A)
Description:
Component of the asymmetric unit membrane (AUM); a highly specialized biomembrane elaborated by terminally differentiated urothelial cells. May play an important role in AUM-cytoskeleton interaction in terminally differentiated urothelial cells. It also contributes to the formation of urothelial glycocalyx which may play an important role in preventing bacterial adherence (By similarity).
Synonyms: UP3a; UPIII; UPK3; UPIIIA
Tractability: Antibody: UniProt predicts a signal peptide or a membrane-spanning region; its Gene Ontology location is reachable by antibodies, with medium confidence.
Gene: Protein-coding gene on chromosome 22 (45,284,924 to 45,295,874, forward strand). Ensembl gene ENSG00000100373.
Subcellular location: Endoplasmic reticulum membrane
Subcellular location (Human Protein Atlas): Nuclear membrane; Nuclear bodies
Gene Ontology:
Molecular function: protein binding
Biological process: epithelial cell differentiation; urea transport; water transport
Cellular component: extracellular exosome; plasma membrane; apical plasma membrane; apical plasma membrane urothelial plaque; endoplasmic reticulum membrane
Genetic constraint (gnomAD): Loss-of-function variants: 32 observed, 27.29 expected, observed/expected ratio (o/e) 1.17, 90% interval 0.88 to 1.57. The upper end of that interval is the gene's LOEUF score, 1.57, which puts it in group 6 of 6, group 1 being the genes least tolerant of losing a copy. Missense variants: 370 observed, 373.01 expected, observed/expected ratio (o/e) 0.99, 90% interval 0.91 to 1.08. Synonymous variants: 171 observed, 164.86 expected, observed/expected ratio (o/e) 1.04, 90% interval 0.92 to 1.18.
Gene-disease validity (ClinGen):
ClinGen rates the evidence that UPK3A causes each of these diseases.
congenital anomaly of kidney and urinary tract (autosomal dominant): Disputed. A urinary system disease characterized by structural malformations in the kidney and/or urinary tract containing vesicoureteral reflux.
Homologues: Orthologues: chimpanzee UPK3A (98% identical), macaque UPK3A (94% identical), pig UPK3A (86% identical), dog UPK3A (85% identical), mouse Upk3a (84% identical), rabbit UPK3A (83% identical), rat Upk3a (82% identical), guinea pig UPK3A (78% identical). Paralogues in human: UPK3B (27% identical), UPK3BL1 (20% identical), UPK3BL2 (20% identical).
Diseases named in the same sentence as UPK3A in open-access papers:
UPK3A is named in the same sentence as 35 diseases in open-access papers, as found by Europe PMC text mining. Sharing a sentence is not in itself a finding about the gene and the disease. The quoted sentences say what the papers report.
bladder cancer (16 papers, 2007 to 2025). "Recently, UPK3A, a structural protein specifically expressed on the membrane of urothelial cells, has gained widespread use in bladder cancer diagnostic research." (PMID 41049846, 2025). "Increasing evidence suggests that UPK3A protein expression not only holds significant diagnostic value but may also be closely associated with the invasiveness, progression, and prognosis of bladder cancer." (PMID 41049846, 2025). "In luminal bladder cancer subtypes, UPK3A protein overexpression has been correlated with distinct transcriptional programs and increased resistance to chemotherapy or immunotherapy." (PMID 41049846, 2025). "Our comprehensive analysis highlights the multifaceted role of UPK3A in bladder cancer pathogenesis and underscores the importance of incorporating molecular, inflammatory, and clinical data to refine prognostic modeling." (PMID 41049846, 2025). "A previous study reported that urine UPK3A level is higher in patients with bladder cancer, and UPK3A in the urine is regarded as a sensitive biomarker for the detection of bladder cancer." (PMID 35774082, 2022). "Bladder cancers developing in Upk3a-CreERT2; Trp53L/L; PtenL/L; Rosa26LSL-Luc mice recapitulated the luminal molecular subtype and papillary architecture of human cancer." (PMID 32546765, 2020). "For example, the gene expression of UPK3A, a promising urinary biomarker for bladder cancer, is highly correlated with SNP rs2742624." (PMID 27409348, 2016). "Downregulated gene products include putative tumor suppressor genes (SCUBE2), factors previously reported as lost in aggressive bladder cancer (FOXA1, GATA3, UPK3A), and metabolizing enzymes with polymorphisms affecting cancer risk (UGT1A10, UGT1A7)." (PMID 24134934, 2013). "Patients with bladder cancer had high UPK3A levels in the urine." (PMID 35774082, 2022). "In 2010, studies showed for the first time that UPK3A can serve as a biomarker for bladder cancer." (PMID 35774082, 2022). "UPK3A, which is specific to the urothelium, is involved in the process of epithelial cell differentiation and cell morphogenesis and has been reported as a reliable marker for bladder cancer detection." (PMID 34631510, 2021). "Only three genes in the bladder cancer pathway were differentially expressed (in particular, they were downregulated) in TCC samples, including the urothelial marker UPK3A." (PMID 35109825, 2022). "In addition, a short peptide (UPK3A 65-84) from Uroplakin 3A (UPK3A) covalently coupled with KLH and CpG as adjuvant was found to be an immunotherapeutic vaccine for bladder cancer." (PMID 30656066, 2019).
urothelial carcinoma (5 papers, 2016 to 2023). A malignant neoplasm derived from the transitional epithelium of the urinary tract (urinary bladder, ureter, urethra, or renal pelvis). "This study showed that genes corresponding to these urothelial lineage markers with the exception of UPK3A were indeed significantly expressed in the urothelial carcinomas as compared to those in prostate adenocarcinomas." (PMID 33762601, 2021). "Interestingly, overexpression of UPK3A is well-documented in urothelial carcinomas, and UPK3A is widely used as a marker of UC by immunohistochemistry in humans and dogs." (PMID 36072391, 2022). "Surprisingly, gene for uroplakin III, UPK3A, was highly expressed in prostate adenocarcinomas as compared to urothelial carcinomas." (PMID 33762601, 2021).
prostate carcinoma (3 papers, 2012 to 2022). A carcinoma that arises from epithelial cells of the prostate gland. "RNA from a dilution series of prostate cancer lines C4-2 and PC3 was prepared, and hybridized to a probe library of six selected genes: KLK3, CD90/THY1, AGR2, HPN, PCA3, UPK3A." (PMID 23029164, 2012).
renal adysplasia (3 papers, 2012 to 2022). "The SULT4A1, PARVB, SCO2, and UPK3A genes are associated with neurological features, macrocephaly/hypotonia, oculopathy, and renal adysplasia, respectively." (PMID 36118903, 2022).
Autoimmunity (2 papers, 2013 to 2023). The occurrence of an immune reaction against the organism's own cells or tissues. "Our study reveals that a UPK3A peptide can induce a peptide-specific CD4+ T cell autoimmunity that mediates painful bladder dysfunction in mice." (PMID 23977210, 2013).
bladder urothelial carcinoma (2 papers, 2021 to 2025). "All urothelial lineage genes had significantly higher expressions in bladder urothelial carcinomas except UPK3A, which was significantly expressed in the prostate adenocarcinomas as compared to bladder urothelial carcinomas (all p < 0.001)." (PMID 33762601, 2021).
vesicoureteral reflux (2 papers, 2020 to 2022). Abnormal flow of urine from the urinary bladder back into the ureters. "A truncating mutation of UPK3A (p.Leu156Valfs*85) was expressed as bilateral vesicoureteral reflux with stage 2 CKD at the age of 4.0 years." (PMID 32164334, 2020).
congenital nephrotic syndrome (1 paper, 2019). "In Fam21 with congenital nephrotic syndrome, both affected children carried two heterozygous mutations in UPK3A." (PMID 31852928, 2019).
gastric cancer (1 paper, 2022). A primary or metastatic malignant neoplasm involving the stomach. "Our study was designed to investigate the underlying mechanism of Uroplakin 3A (UPK3A) in gastric cancer." (PMID 35774082, 2022). "KEGG pathway enrichment analysis was performed to explore the downstream signaling pathway that is modulated by UPK3A in gastric cancer." (PMID 35774082, 2022). "In this study, we demonstrate that UPK3A plays an oncogenic role in the progression of gastric cancer in vitro." (PMID 35774082, 2022). "UPK3A was markedly upregulated in gastric cancer tissues compared to that in normal tissues, and patients with high UPK3A level showed poor prognosis." (PMID 35774082, 2022). "Collectively, silencing of UPK3A inhibited the migration and invasion of gastric cancer cells, indicating that UPK3A promotes the progression of gastric cancer." (PMID 35774082, 2022). "In the present study, we demonstrated that UPK3A is highly expressed in gastric cancer cells, and UPK3A silencing represses the proliferation and migration of gastric cancer cells." (PMID 35774082, 2022). "UPK3A was markedly upregulated in gastric cancer tissues compared to that in normal tissues (P < 0.01)." (PMID 35774082, 2022). "In the present study, the oncogenic function of UPK3A in human gastric cancer cells was investigated." (PMID 35774082, 2022). "The analysis results indicated that UPK3A levels were significantly correlated with the prognosis of patients with gastric cancer (P < 0.001) and that patients with high UPK3A levels had poor prognoses." (PMID 35774082, 2022). "The viability, proliferation, migration, and invasion of SNU-216 and HGC-27 were significantly decreased upon UPK3A silencing, indicating that UPK3A promotes the progression of gastric cancer." (PMID 35774082, 2022). "UPK3A was highly expressed in human gastric cancer cell lines compared to that in a normal human gastric epithelial cell line." (PMID 35774082, 2022). "TCGA analysis found Uroplakin 3A (UPK3A) was upregulated in gastric cancer tissues." (PMID 35774082, 2022). "Silencing of UPK3A inhibited the proliferation, migration, and invasion of gastric cancer cells." (PMID 35774082, 2022). "UPK3A expression was significantly upregulated in gastric cancer cells." (PMID 35774082, 2022). "We further explored the mechanism of UPK3A promoting the progression of gastric cancer." (PMID 35774082, 2022). "In our study, we first examined the effect of UPK3A on gastric cancer cells." (PMID 35774082, 2022). "Furthermore, there are effects of UPK3A silencing on the activity, proliferation, migration, and invasion of human gastric cancer cells (SNU-216 and HGC-27) using 3-(4,5-dimethylthiazol-2-yl)-2,5-diphenyltetrazolium bromide (MTT), colony formation, wound healing, and Transwell assays." (PMID 35774082, 2022). "Our findings indicate that UPK3A may be a potential target for the treatment of gastric cancer." (PMID 35774082, 2022). "However, the role of UPK3A in the progression of gastric cancer remains unclear." (PMID 35774082, 2022).
polycystic kidney disease (1 paper, 2020). A usually autosomal dominant and less frequently autosomal recessive genetic disorder characterized by the presence of numerous cysts in the kidneys leading to end-stage renal failure. "Genetic abnormalities such as autosomal dominant or recessive inheritance of polycystic kidney disease, hereditary kidney dysplasia, caused by RET and UPK3A gene mutations and chromosomal abnormalities, can result in developmental abnormalities and lead to Potter sequence." (PMID 32347825, 2020).
renal hypodysplasia/aplasia 1 (1 paper, 2025). "The region could be functionally important since human UPK3A mutations I119T, G120E and D121Y are currently associated with Renal hypodysplasia/aplasia 1 (according to ClinVar)." (PMID 40743127, 2025).
tumor (21 papers, 2017 to 2026). "Several studies have demonstrated that elevated expression of UPK3A protein is associated with advanced tumor stages, aggressive phenotypes, and shorter survival in BUC patients." (PMID 41049846, 2025). "A second key finding of this study is the absence of correlation between D2 and the classical urothelial differentiation markers GATA3 and UPK3A in both non-tumor and BLCA plasma samples." (PMID 41585944, 2026). "In contrast, GATA3 and UPK3A displayed a moderate positive correlation in tumor samples (Pearson correlation coefficient, rho, ρ = 0.50), as expected for established BLCA-associated transcripts." (PMID 41585944, 2026). "While GATA3 and UPK3A exhibited the expected coordinated behavior in tumor plasma samples, reflecting their shared urothelial lineage specificity, D2 varied independently from both transcripts across all conditions." (PMID 41585944, 2026). "A similar trend was observed for GATA3 (p < 0.05) and UPK3A, two well established BLCA-associated markers, supporting the presence of tumor-related transcriptional signatures in circulation." (PMID 41585944, 2026). "The final selected features included age, smoking history, positive urine bacterial culture, perineural invasion, vascular invasion, muscle layer invasion (M stage), UPK3A expression, tumor number, tumor boundary characteristics, and necrosis." (PMID 41049846, 2025). "A recent study describes a more faithful murine BCa model that carries Upk3a-CreERT2; Trp53L/L; PtenL/L; Rosa26LSL–Luc tumor applied to excavate the biology of BCa." (PMID 33681207, 2021). "It was also found that excessive Mettl3 in cells of Upk3a origin contributed to promoting tumor growth by measuring tumor mass in mice." (PMID 33681207, 2021). "Comparing tumor bulk in Upk3aCreER wild-type and KI mice, the mice bearing BCa with overexpressed Mettl3 in Upk3a-derived cells developed tumors more aggressively." (PMID 33681207, 2021). "However, correlation analyses revealed that D2 expression varied independently from GATA3 and UPK3A across both tumor and non-tumor groups." (PMID 41585944, 2026). "SHAP analysis highlighted vascular invasion, tumor necrosis, and UPK3A protein as key predictors." (PMID 41049846, 2025). "In the non-tumor group, D2 showed no positive association with either GATA3 (Pearson correlation coefficient, rho, ρ = −0.18) or UPK3A (Pearson correlation coefficient, rho, ρ = −0.12)." (PMID 41585944, 2026). "Using antibodies against urothelial differentiation markers, the tumor was negative for uroplakin 3a, whilst cytokeratin (CK) 20 expression was weak and confined to the central region of the tumor." (PMID 31552026, 2019).
cancer (7 papers, 2008 to 2022). A tumor composed of atypical neoplastic, often pleomorphic cells that invade other tissues. "Our established BC 3D organoids expressed urothelial markers (CK7, CK20, and UPK3A), showed the response to anti-cancer drugs, and exhibited tumorigenesis." (PMID 32523078, 2020). "UPK3A, FAM3D, and LCN2, which participate cancer cell metabolisim, were also downregulated in all PDOs after CUL4B ablation." (PMID 32054830, 2020).
infection (2 papers, 2009 to 2023). The state of being infected such as from the introduction of a foreign agent such as serum, vaccine, antigenic substance or organism. "However, uroplakin 3a (Upk3a), a surface protein expressed by differentiated urothelial cells, was only significantly increased in cells grown in 5% CM but not in 50% CM, as determined at 7 d post-infection." (PMID 37037942, 2023).
kidney disorder (1 paper, 2022). A disease involving the kidney. "The genes UPK3A, FBLN1, WNT7B, and CELSR1 have the strongest evidence of association with kidney disorders." (PMID 35741804, 2022). "The results from this study suggest that UPK3A, FBLN1, WNT7B, and CELSR1 are strong candidate genes for kidney disorders in PMS and merit functional studies." (PMID 35741804, 2022). "Using association analysis, candidate gene prioritization based upon a set of known kidney-related genes and estimates of haploinsufficiency, we identified UPK3A, FBLN1, WNT7B, and CELSR1 as priority candidate genes for kidney disorders." (PMID 35741804, 2022).
UPK3A also shares sentences with these, for which no sentence is quoted: squamous cell carcinoma (3 papers); bladder (2); bladder infection (2); meningioma (2); Bardet-Biedl syndrome (1); benign prostatic hyperplasia (1); colon cancer (1); cystitis (1); germ cell tumor (1); intellectual impairment (1); melanoma (1); ovarian neoplasm (1); Phelan-McDermid syndrome (1); prostate adenocarcinoma (1); renal cell carcinoma (1); renal tumor (1); Ureteral obstruction (1); urinary tract infection (1); urolithiasis (1); urological diseases (1).